ASPN (asporin)
Diseases named in the same sentence as ASPN in open-access papers (continued):
Sharing a sentence is not in itself a finding about the gene and the disease.
stomach adenocarcinoma (2 papers, 2021 to 2025). "The association between ASPN expression and clinical features of GC patients with respect to tumor stage was analyzed using TCGA data on stomach adenocarcinoma (STAD)." (PMID 34379688, 2021). "In the TCGA stomach adenocarcinoma dataset, ASPN was significantly upregulated in tumor samples compared with normal samples (p = 2.5e− 07, Wilcoxon test)." (PMID 39905493, 2025).
triple-negative breast carcinoma (2 papers, 2015 to 2019). An invasive breast carcinoma which is negative for expression of estrogen receptor (ER), progesterone receptor (PR), and human epidermal growth factor receptor 2 (HER2). "While hormone receptor (HR) positive cells cause strong asporin expression, triple-negative breast cancer (TNBC) cells suppress it." (PMID 26327350, 2015). "Although decorin is regarded as the “endogenous guardian” and biglycan acts as a danger signal in cancer, asporin acts as an oncogene in some types of cancer (breast, pancreatic, colorectal, gastric, and prostate), but as a tumor suppressor gene in triple-negative breast cancer." (PMID 31608236, 2019). "It is therefore not surprising that under different conditions, asporin acts as a tumor suppressor gene in triple-negative breast cancer and as an oncogene in colorectal cancer." (PMID 31608236, 2019). "The results indicated that tumorigenic and highly metastatic triple-negative breast cancer (TNBC) cells of the basal-like subtype (e.g., MDA-MB-231 and MDA-MB-468) did not induce asporin expression in NBFs." (PMID 26327350, 2015).
Acetabular dysplasia (1 paper, 2023). A smaller than normal acetabulum that has insufficient femoral head coverage leading to abnormal hip joint contact pressures, instability and pain. "Copy number loss in the ASPN gene region may be involved in the pathogenesis of acetabular dysplasia." (PMID 37082197, 2023).
B-cell non-Hodgkin lymphoma (1 paper, 2022). The most common type of non-Hodgkin lymphoma. "Interestingly, a subset of the members in the SLRP protein family have been previously identified in B-cell Non-Hodgkin’s lymphomas including DCN, BGN, ASPN, FMOD, LUM, PRELP, and TSKU." (PMID 36873459, 2022).
calcific aortic valve disease (1 paper, 2020). "Asporin-dependent regulation of aortic valve mineralization with a concomitant expression of procalcific Wnt/β-catenin signaling has not been well studied before, especially in the case of adult calcific aortic valve disease or CAVD." (PMID 32328102, 2020). "Overall, all these data are highly indicative that Asporin might be a novel biomolecular target to treat patients of calcific aortic valve disease over current cusp replacement surgery." (PMID 32328102, 2020).
cardiomyopathy (1 paper, 2017). A disease of the heart muscle or myocardium proper. "Analysis of pathways that were dysregulated across cardiomyopathy phenotypes identified shared genes that were associated with extracellular matrix remodeling and thus likely fibrosis (THY1, CILP, OGN, THBS4, ASPN, HAPLN1,and SMOC2), as well as calcium (ADIPOQ, ASPN, THBS4, STAT4, and SMOC2)." (PMID 28098235, 2017).
cartilage disease (1 paper, 2021). Softening and degeneration of the CARTILAGE. "Interactions between ASPN and TGFβ have been subjected to intense investigations in various bone and cartilage diseases; however, the mechanism of action is vastly different in GC." (PMID 34379688, 2021).
clubfoot (1 paper, 2022). The most common congenital deformation of the foot, occurring in 1 of 1,000 live births. "In our previous study, we detected changes in the composition of the ECM in the contracted M-side tissue of relapsed clubfoot—an increase in collagen III, V and VI, TGF-βIP, asporin, tenascin C, and qualitative changes in the distribution of TGF-β7." (PMID 35292718, 2022).
encephalitis (1 paper, 2025). An acute inflammatory process affecting the brain parenchyma. "The resultsindicated that in the encephalitis group, potassium channel-related gene KCNN3,cell development-related genes EMC8, DANCR, and ASPN, along with thetranscription factor ZNF296, were significantly upregulated." (PMID 40985687, 2025).
endometriosis (1 paper, 2022). The growth of functional endometrial tissue in anatomic sites outside the uterine body. "According to the findings of logistic regression models, elevated ASPN expression is an independent risk factor in the development of endometriosis, suggesting that abnormal expression of ASPN is closely related to the development of endometriosis." (PMID 36011263, 2022). "Exploring the molecular mechanisms associated with ASPN in endometriosis will help further investigate new targeted therapeutic approaches." (PMID 36011263, 2022). "The results of constructing univariate and multivariate logistic regression models showed that high expression of ASPN was an independent risk factor for the development of endometriosis, suggesting that abnormal expression of ASPN is closely related to the development of endometriosis." (PMID 36011263, 2022). "Aberrant expression of ASPN is associated with the formation of the immune microenvironment and may play a vital role in the onset, advancement, metastasis, and immune response of endometriosis." (PMID 36011263, 2022). "Univariate and multivariate logistic regression analysis showed that ASPN expression was an independent influencing factor in patients with endometriosis." (PMID 36011263, 2022). "mRNA and protein expression of ASPN was found to be higher in the endometriosis group than in normal endometrial tissue (p = 0.019, n = 12 vs. 12; p = 0.0013, n = 10 vs. 10)." (PMID 36011263, 2022). "To determine the potential function of ASPN and its impact on endometriosis, based on the median of ASPN as the cutoff value, we split our 401 samples into two groups, one with high ASPN expression and one with low ASPN expression." (PMID 36011263, 2022). "Further in vitro and in vitro experiments are needed to elucidate the detailed mechanism of ASPN’s involvement in the pathogenesis of endometriosis." (PMID 36011263, 2022). "To determine the potential function of ASPN and its potential impact on endometriosis, we performed GO and KEGG enrichment analysis of 255 differential genes between high- and low-expression groups." (PMID 36011263, 2022). "By studying the relationship between ASPN, immune infiltration, and immune checkpoint genes, we can better understand the molecular immune mechanisms involved in the pathogenesis of endometriosis." (PMID 36011263, 2022). "Univariate and multifactorial logistic regression models were further constructed to analyze the correlation between ASPN expression and the clinical characteristics of patients with endometriosis." (PMID 36011263, 2022). "In the present study, for the first time, we discovered that ASPN is strongly expressed in endometriosis and is related to immune cell infiltration, particularly T cells, B cells, and NK cells." (PMID 36011263, 2022). "However, further experiments are needed to validate the mechanisms of these pathways regulated by ASPN in endometriosis." (PMID 36011263, 2022). "This suggests that ASPN is a potential co-regulator of immune checkpoints in endometriosis." (PMID 36011263, 2022). "In the clinical case-cohort we collected, the sensitivity of ASPN was 91.7%, and the specificity was 66.7%, which suggests that ASPN may be a potential biomarker for the diagnosis of endometriosis." (PMID 36011263, 2022). "ASPN mRNA expression levels were significantly elevated in patients with endometriosis." (PMID 36011263, 2022). "ASPN is considered a new potential biomarker involved in the pathogenesis of endometriosis." (PMID 36011263, 2022). "This suggests that ASPN may be a promising biomarker for differentiating endometriosis from normal controls." (PMID 36011263, 2022). "The study found that ASPN may be a new biomarker for endometriosis." (PMID 36011263, 2022). "The relative expression of mRNA for ASPN and GEM was found to be higher in endometriosis tissues than in normal controls by qRT-PCR (p = 0.004, p = 0.039; n = 6 vs. 6)." (PMID 36011263, 2022).
endometriosis (continued). "Immune cell infiltration and immune dysfunction in the immune microenvironment of endometriosis are involved in the development of the disease; however, the relationship between immune infiltration and ASPN expression has not been reported." (PMID 36011263, 2022). "In this study, we found for the first time that ASPN was highly expressed in endometriosis tissues and was also correlated with patients’ age (p = 0.03), r-AFS stage (p = 0.006), and lesion location (p < 0.001), suggesting a positive correlation between ASPN and the severity of endometriosis." (PMID 36011263, 2022).
gastric tumor (1 paper, 2021). "Given our observation that increased expression of ASPN in gastric tumor tissue triggers EMT phenotype and copiously produces collagen I, distinct expression changes associated with angiogenesis were determined by evaluating the expression of VEGF." (PMID 34379688, 2021). "The results indicated that DCN and TGFβ formed a complex and possibly interacted with each other in normal tissues, whereas ASPN and TGFβ predominantly interacted with each other in gastric tumor tissues." (PMID 34379688, 2021). "Our findings indicated that overexpressed ASPN interacts with TGFβ in gastric tumor epithelium and possibly triggers the EMT." (PMID 34379688, 2021).
gastritis (1 paper, 2025). Inflammation of the stomach. "In the GSE130823 dataset, ASPN was upregulated in HGIN and GC samples compared with gastritis samples (HGIN: p = 0.082, Wilcoxon test; GC: p = 0.087, Wilcoxon test)." (PMID 39905493, 2025).
hip osteoarthritis (1 paper, 2007). "Asporin is a cartilage extracellular protein that has been reported to be associated with knee and hip osteoarthritis." (PMID 17389037, 2007).
invasive ductal carcinoma (1 paper, 2014). "Their study reported that ASPN is highly upregulated in invasive ductal carcinoma (IDC), possibly associated with invasion, and related to the epithelial-mesenchymal transition." (PMID 24982892, 2014).
leiomyoma (1 paper, 2019). A well-circumscribed benign smooth muscle neoplasm characterized by the presence of spindle cells with cigar-shaped nuclei, interlacing fascicles, and a whorled pattern. "They identified several proteins up regulated in the leiomyoma: POSTN, TNC, COL3A1, COL24A1, and ASPN." (PMID 31100862, 2019).
lymphedema (1 paper, 2025). Excess fluid collection in tissues, causing swelling. "Additionally, using an independent dataset, we observed that only ASPN was significantly upregulated in patients with long-term CRL (duration >14 years)—a pattern that aligns closely with the chronic progression of fibrosis in lymphedema." (PMID 40881699, 2025). "Further expression analysis revealed that only four of these genes(POSTN, ASPN, FMOD, and MFAP5) exhibited statistically significant differential expression between lymphedema and control tissues, indicating their potential biological relevance in the fibrosis pathogenesis of lymphedema." (PMID 40881699, 2025).
metastasis (1 paper, 2022). The spread or migration of cancer cells from one part of the body (where they first appeared) to another. "Our analysis was limited to four genes, ASPN, POSTN, SPARCL1, and MCAM, which we determined as potential markers of stromal activation in a xenograft model of PC bone metastasis." (PMID 36185585, 2022).
metastatic cancer (1 paper, 2022). A carcinoma which has spread from the original site of growth to another anatomic site. "Compared with the group of acid‐insensitive analogs of ASPN (namely AIPN), the ASPN group eliminated metastatic cancer cells more efficiently." (PMID 34927373, 2022).
metastatic prostate carcinoma (1 paper, 2025). A carcinoma that arises from the prostate gland and has spread to other anatomic sites. "Importantly, over half of metastatic sites demonstrated expression of HER2 and HER3 with stromal expression of ASPN, suggesting this signaling mechanism may have critical roles in metastatic prostate cancer." (PMID 40857406, 2025). "Together, these results identify ASPN as a HER3 ligand and suggest potential clinical utility of anti-HER2 or anti-HER3 ADCs for the treatment of metastatic prostate cancer." (PMID 40857406, 2025).
myelofibrosis (1 paper, 2018). A partial or complete replacement of the bone marrow stroma by fibrous tissue. "Importantly, upregulation of CXCL12, ASPN, and OLFM3, factors secreted by CAF, has been observed; CXCL12, through the interaction with its receptor CXCR4, can lead to CXCL12 and TGFβ production and concur to myelofibrosis." (PMID 29515580, 2018).
myocardial infarction (1 paper, 2020). Gross necrosis of the myocardium, as a result of interruption of the blood supply to the area, as in coronary thrombosis. "Upregulation of asporin has been observed during ECM remodeling in a pig model of myocardial infarction, but further work is required to establish the importance of asporin in RV function." (PMID 32805183, 2020).
osteophytes (1 paper, 2017). "In addition, we identified a rare missense SNP rs41278695 resulting in an amino acid change Gly193Glu in the human ASPN gene among hand OA patients with osteophytes." (PMID 29233086, 2017).
tendinopathy (1 paper, 2020). "Moreover, asporin regulates collagen mineralization, which is a common mechanism of tendinopathy." (PMID 32656202, 2020).
thyroid cancer (1 paper, 2022). "To further examine the ability of asporin to enhance tumor progression in thyroid cancer, we knocked down endogenous asporin expression in thyroid cancer cell lines by transfection with three siRNAs." (PMID 35600399, 2022). "The present study contributes to this field by demonstrating that asporin interacts with HER2 to promote thyroid cancer metastasis by regulating the MAPK-epithelial-to-mesenchymal transition (EMT) axis." (PMID 35600399, 2022). "Furthermore, siASPN also decreased the number of colonies in the colony formation assays, further indicating that asporin knockdown inhibits the growth of thyroid cancer cells." (PMID 35600399, 2022). "However, the mechanism by which asporin regulates HER2 expression in thyroid cancer remains to be fully elucidated." (PMID 35600399, 2022). "Functionally, asporin is mainly expressed in the extracellular matrix, cell membrane, and cytoplasm of PTC tumorous tissues, and promotes thyroid cancer cell proliferation, migration, and invasion." (PMID 35600399, 2022). "Asporin was found to be expressed mainly in the extracellular matrix, cell membrane, and cytoplasm of PTC tumorous tissues, and promoted thyroid cancer cell proliferation, migration, and invasion." (PMID 35600399, 2022). "A previous study indicated that asporin is expressed at moderate levels in thyroid normal tissues; however, the biological roles of asporin in thyroid cancer progression have never been investigated." (PMID 35600399, 2022).
tumor (62 papers, 2010 to 2026). "Of note, ASPN, a small leucine-rich proteoglycan expressed predominantly by cancer-associated fibroblasts (CAFs), plays a pivotal role in tumor progression by playing a role in modulating the TME." (PMID 39007269, 2024). "Asporin is a stroma-derived inhibitor of TGFβ1 and a tumor suppressor in BC, where high asporin expression is significantly associated with less aggressive tumors when stratifying patients according to the clinical outcome." (PMID 37046676, 2023). "ASPN is predominantly secreted from cancer-associated fibroblasts (CAFs) in a variety of tumors and is correlated with tumor invasion and metastasis." (PMID 34379688, 2021). "ASPN expression is increased in fibroblasts of tumour stroma, and loss of ASPN prevents self-renewal of mesenchymal stromal cells." (PMID 33889572, 2021). "Overall, in the TCGA dataset of STAD, consistent upregulation of ASPN expression was statistically associated with increasing tumor stage." (PMID 34379688, 2021). "The up-regulated protein ASPN has been reported to reside in the tumor stroma and promote co-invasion of cancer-associated fibroblasts and cancer cells." (PMID 29520031, 2018). "Additionally, ASPN, a stromal gene implicated in tumor progression, was also highly expressed in PNI-positive tumors." (PMID 40868045, 2025). "Whether one predominates over the other depends strongly on how advanced the tumour lesion is, as in low-grade lesions and high asporin levels are associated with a better outcome, whereas in more advanced ones, prognosis is significantly worse." (PMID 41463344, 2025). "Our results thereby indicate that over expression of ASPN in GC tumor tissue and its enhanced association with TGFβ probably triggers the canonical TGFβ signaling pathway, which was reflected by significantly higher levels of phosphorylated pSMAD2 compared to adjacent normal tissue." (PMID 34379688, 2021). "In conclusion, asporin also serves as a context-dependent regulator of BC progression via the TGFβ/Smad pathway and demonstrates an enhanced sensitivity to the tumour subtype and microenvironmental stimuli." (PMID 41463344, 2025). "In the relma-cel study, the expression levels of tumor-associated fibroblast markers (AP, TNC, CSPG4, PDGFRA, S100A4, ASPN, STC1, and ITGAM) were higher in the patients with PR than with CR." (PMID 39858099, 2025). "Of note, high levels of asporin are found in tumoural lesions and are even greater in the invasive ductal carcinoma tumours than in ductal carcinoma in situ lesions." (PMID 41463344, 2025). "For example, elevated Asporin (ASPN) expression in oxaliplatin-resistant CRC was targeted using nanoparticles co-delivering ASPN-siRNA and oxaliplatin, resulting in improved anti-tumor activity in vitro and in vivo." (PMID 40777019, 2025). "Asporin (ASPN), a small leucine-rich proteoglycan expressed predominantly by cancer associated fibroblasts (CAFs), plays a pivotal role in tumor progression." (PMID 40230452, 2025). "Theses 13 genes (e.g., COL1A1, POSTN, ASPN, PDGFRA, MUC4, SPARC), implicated notably in EMT and cancer progression, were found to be highly expressed in depth of tumor ID15 and ID08, near the invasive margin." (PMID 40076457, 2025). "We previously identified that ASPN (asporin/PLAP-1) mRNA was higher in canine OSA tumours as compared to normal bone (p = 0.02175), and the present study exhibited human OSA overexpression (p = 0.000978)." (PMID 40566602, 2025). "For example, Yuto Sasaki and colleagues discovered that asporin (ASPN) is a leucine-rich small proteoglycan mainly expressed by cancer-associated fibroblasts (CAFs), playing a crucial role in tumor progression." (PMID 39179991, 2024). "LUM, COL18A1, BGN, PRELP, and ASPN showed increased expression in tumor tissue compared to the paired NAT tissue, inconsistent with the declined trend in other histologic subtypes." (PMID 39305996, 2024).